RUNX1 (RUNX family transcription factor 1)
Diseases named in the same sentence as RUNX1 in open-access papers (continued):
Sharing a sentence is not in itself a finding about the gene and the disease.
steatosis (5 papers, 2019 to 2023). Increased lipid within the cytoplasm of cells. "Several factors could have led to an increased expression of RUNX1 in the LSECs, including an increase in steatosis." (PMID 34445195, 2021). "This study reports that steatosis-induced RUNX1 augmented the expression of adhesion and angiogenic molecules and properties in ECs and may be involved in enhancing inflammation and disease severity in NASH." (PMID 31635436, 2019). "RUNX1, runt-related transcription factor 1; NAFLD, nonalcoholic fatty liver disease; SS, simple steatosis; NASH, nonalcoholic steatohepatitis." (PMID 35740337, 2022). "Previous studies from our lab have shown that liver RUNX1 expression is upregulated in patients with NASH and correlates significantly with their steatosis and inflammatory grades." (PMID 34445195, 2021). "In the present study, it is worth noting that hepatic RUNX1 and FAS expression were increased in the steatosis process of patients with MO, but in NASH, their expression was diminished or not increased." (PMID 34063472, 2021). "Quantitative RT-PCRs and a transcription factor analysis of angiogenesis-associated differentially expressed genes in liver tissues of healthy controls, patients with steatosis and NASH, indicated a potential role of RUNX1 in NASH." (PMID 31635436, 2019). "RUNX1 mRNA expression demonstrated a significant positive correlation with NAS, steatosis and inflammation degree." (PMID 31635436, 2019). "RUNX1 target genes, CCL2 and PIK3CA significantly correlated to NAS, steatosis, inflammation grade and fibrosis score, NOS3 to NAS and inflammation grade and PRKCE to NAS and steatosis grade." (PMID 31635436, 2019).
acute kidney injury (4 papers, 2021 to 2025). Sudden and sustained deterioration of the kidney function characterized by decreased glomerular filtration rate, increased serum creatinine or oliguria. "AKI (acute kidney injury); RUNX1 (runt-related transcription factor 1); SNHG5 (small nuclear RNA host gene 5); TLR4/NF-ĸb (toll-like receptor 4/nuclear factor-ĸB); I/R (ischemia/reperfusion); DR6 (death receptor 6)." (PMID 40217756, 2025).
allergies (4 papers, 2022 to 2023). "Furthermore, a two-sample MR approach leveraging large GWAS and eQTL databases suggested a potential causal role for IL4, IL1RL1, RP11-13A1.1, FCER1A and MS4A2, RUNX1, and ACLS6 expression in various allergic diseases and serum IgE levels." (PMID 36725846, 2023).
depression (4 papers, 2019 to 2026). "We found association of the GHR gene (false discovery rate -FDR- = 0.03, z = 4.2) and Reactome "RUNX1-regulated transcription of genes involved in myeloid cell differentiation pathway" (FDR = 0.016, beta = 1.2) with depression in GS." (PMID 41856978, 2026).
head and neck squamous cell carcinoma (4 papers, 2016 to 2024). A squamous cell carcinoma that arises from any of the following anatomic sites: lip and oral cavity, nasal cavity, paranasal sinuses, pharynx, larynx, and salivary glands. "For instance, in patients with head and neck squamous cell carcinoma (HNSCC), elevated levels of RUNX1 are associated with more advanced disease stages, as indicated by American Joint Committee on Cancer staging, T-staging, and N-staging." (PMID 38430423, 2024). "In head and neck squamous cell carcinoma (HNSCC), RUNX1 with high expression was associated with tumorigenicity of HNSCC." (PMID 34606420, 2021). "According to the data from GEPIA, RUNX1 expression was found to be positively related to TTN-AS1 expression in head and neck squamous cell carcinoma samples." (PMID 34606420, 2021). "It has been reported that the suppression of RUNX1 inhibited cell proliferation, migration, and invasion in head and neck squamous cell carcinoma (HNSCC)." (PMID 36982956, 2023).
Hypertension (4 papers, 2021 to 2023). The presence of chronic increased pressure in the systemic arterial system. "RUNX1 in monocytes/macrophages is associated with the development of IA via the expression of NFKB1 among patients with hypertension." (PMID 35655614, 2022). "Among patients with hypertension, RUNX1 in monocytes and macrophages was associated with a higher risk of IA through its regulation of NFKB1." (PMID 35655614, 2022). "RUNX1 is involved in endothelial cells and hematopoietic processes, thereby affecting endothelial function and inflammatory changes, and the abnormal expression of RUNX1 can induce hypertension." (PMID 35655614, 2022). "Previous studies have found that RUNX1 is involved in hypertension progression to some extent." (PMID 35655614, 2022). "Based on the functions played by RUNX1 in the progression of hypertension and IA, we hypothesized that RUNX1 promotes hypertension progression combined with IA." (PMID 35655614, 2022). "RUNX1 might be a hub gene between hypertension, IA, and DEGs in monocytes." (PMID 35655614, 2022).
invasive ductal carcinoma (4 papers, 2016 to 2024). "We further analysed the association between AXIN1 and RUNX1 at the protein level using a commercial tumour microarray, TMA-1007, which included among others duplicate cores from 31 ER+ invasive ductal carcinomas in which ER was expressed at either low (ERlow) or high levels (ERhigh)." (PMID 26916619, 2016). "In ductal adenocarcinoma of the breast, FOXA1, together with EP300 and RUNX1, enhances E-cadherin promoter activity in metastatic breast cancer cells." (PMID 38605023, 2024).
leukopenia (4 papers, 2018 to 2026). "ABCC4 Glu757Lys showed an association with leukopenia, and rs2834826 located upstream of RUNX1 showed an association in the conditional analysis on NUDT15 Arg139Cys." (PMID 29923122, 2018). "RUNX1 variants (n = 8) were associated with leukopenia (p = 0.012)." (PMID 42195121, 2026). "No additional SNPs were found in the conditional GWAS; therefore, we included the genotype of NUDT15 codon 139 or NUDT15 haplotype, ABCC4, and RUNX1 in the logistic regression models to predict thiopurine-induced severe leukopenia and alopecia." (PMID 29923122, 2018). "Runt-related transcription factor 1 (RUNX1) was reported to play an important role in hematopoiesis, and rs2834826 located upstream of this gene was found to be significantly associated with leukopenia in Korean IBD." (PMID 29923122, 2018).
myelofibrosis (4 papers, 2020 to 2023). A partial or complete replacement of the bone marrow stroma by fibrous tissue. "Consistent with this, CAR cells from PMF mice with myelofibrosis displayed reduced expression of Runx1 and Runx2 compared with control animals." (PMID 35551452, 2022). "Our results raise the possibility that hematopoietic cells with the driver mutations found in myelofibrosis act on HSC cellular niches (CAR cells) to reduce their Runx1/2 expression, resulting in an increase in myelofibrosis." (PMID 35551452, 2022). "Thus, mutations or chromosomal rearrangements involving Runx1 and/or Runx2 would not contribute to progression of myelofibrosis." (PMID 35551452, 2022).
neutropenia (4 papers, 2022 to 2026). A decrease in the number of neutrophils found in the blood. "Using in vivo murine MDS models driven by RUNX1- or Nup98-Hoxd13, we found that animals with knockdown of Fbox11 had exacerbated neutropenia compared with animals with intact Fbxo11." (PMID 41542766, 2026).
non-alcoholic steatohepatitis (4 papers, 2020 to 2022). "RUNX1 is involved in angiogenesis, which is crucial in inflammation, but its role in nonalcoholic steatohepatitis (NASH) remains unclear." (PMID 34063472, 2021).
pulmonary hypertension (4 papers, 2022 to 2025). Increased pressure within the pulmonary circulation due to lung or heart disorder. "An experimental study has shown that the inhibition of RUNX1 expression decreases pulmonary hypertension progression in mice." (PMID 35655614, 2022). "Finally, we review the results of recent studies from our lab demonstrating the efficacy of preventing and reversing pulmonary hypertension in animal models of PAH by deleting RUNX1 expression in endothelial or myeloid cells or by the use of RUNX1 inhibitors." (PMID 38028440, 2023). "Studies in our lab aimed at testing this hypothesis by examining the effect of suppressed Sox17 expression on the expression of Runx1 in the lung and in progenitor cells of animals with pulmonary hypertension and patients with PAH are ongoing." (PMID 38028440, 2023). "We also found that RUNX1 expression is higher in circulating EPCs in mice with Sugen/hypoxia-induced pulmonary hypertension (SuHx-PH) and in patients with PAH, compared to EPCs obtained from control mice or healthy volunteers, respectively." (PMID 38028440, 2023).
renal cell carcinoma (4 papers, 2016 to 2024). "Of notable interest is RUNX1, which is highly expressed in renal cell carcinoma compared with normal kidney tissue." (PMID 38724670, 2024). "For instance, the RUNX1 with high expression in renal cell carcinoma is related to poor prognosis." (PMID 34606420, 2021).
systemic mastocytosis (4 papers, 2023 to 2025). Systemic mastocytosis (SM) comprises a heterogeneous group of rare acquired and chronic hematological malignancies that are related to an abnormal proliferation of mast cells in tissue, including bone marrow, with or without skin involvement. "Other somatic gene alterations implicated in some cases of advanced systemic mastocytosis include mutations in TET2, SRSF2, ASXL1, RUNX1, CBL, JAK2, NRAS, and KRAS." (PMID 41440762, 2025). "Midostaurin treatment in systemic mastocytosis patients has shown that patients with one or more mutations in the S/A/R (SRSF2, ASXL, or RUNX1) panel have a lower survival rate and a higher progression rate to AML or mast cell leukemia than patients without mutations." (PMID 38007419, 2023). "Interestingly, NGS analysis did not detect any mutations in all the other KIT exons analyzed nor in other genes previously reported in patients with advanced systemic mastocytosis (TET2, SRSF2, ASXL1, RUNX1, CBL, JAK2, NRAS, and KRAS)." (PMID 41440762, 2025).
type 2 diabetes (4 papers, 2021 to 2024). "Taken together, our data suggest that IGFBP7 is differentially expressed in islets in type 2 diabetes and that IGFBP7 may be regulated by RUNX1." (PMID 39280605, 2024). "A 6-month training study in males with and without a family history of type 2 diabetes showed decreased DNA methylation of genes with known function in muscle and type 2 diabetes, including MEF2A, RUNX1, NDUFC2, and THADA, decreased after exercise." (PMID 35323665, 2022).
aplastic anemia (3 papers, 2012 to 2026). Anemia resulting from bone marrow failure (aplastic or hypoplastic bone marrow). "Complex structural anomalies of chromosome 21 were present in two of these patients, leading to the disruption or to the loss of the RUNX1 gene, with decreased expression and different haematological and clinical pictures: severe aplastic anaemia (SAA) and congenital thrombocytopenia." (PMID 23025896, 2012). "Chromosome anomalies were found in the BM of three patients, without any morphological evidence of MDS: 1) an acquired complex rearrangement of chromosome 21 in a boy with severe aplastic anaemia (SAA); the rearrangement caused the loss of exons 2–8 of the RUNX1 gene with subsequent hypoexpression." (PMID 23025896, 2012).
bladder cancer (3 papers, 2020 to 2022). "RUNX1 is a novel direct target of miR-27a, which is involved in the regulation of sensitivity to bladder cancer chemotherapy." (PMID 32655621, 2020). "Next, we examined the mutations in these genes in bladder cancer and found that the mutation frequency of PTGER4 was the highest, reaching 9%, with amplification mutations as the main mutation; it was followed by RUNX1, IL7, and CIITA, with mutation frequencies of 6, 5, and 5%, respectively." (PMID 32655621, 2020). "Some of these genes were closely related to the occurrence and development of bladder cancer: CDK6, IL-10, and RUNX1, of which CDK4/6 inhibitors are a promising treatment strategy for the treatment of bladder cancer." (PMID 32655621, 2020).
bone marrow failure (3 papers, 2020 to 2023). "Moreover, a comparison of TLs amongst patients carrying mutations in the genes related to bone marrow failure demonstrated that patients with mutations in LIG4 or RUNX1 had the shortest TLs." (PMID 36672189, 2023). "Double knockout (DKO) mice of Runx1 and Runx3 showed co-occurrence of bone marrow failure (BMF) and myeloproliferative disorder (MPD)." (PMID 36672189, 2023).
brain injury (3 papers, 2013 to 2023). Acute and chronic (see also brain INJURIES, CHRONIC) injuries to the brain, including the cerebral hemispheres, CEREBELLUM, and brain STEM. "The Runx1 locus exhibited increased accessibility in Ts65Dn microglia; RUNX1 is a TF that modulates microglial gene expression during early postnatal life, but can increase in adults following brain injury or infection to promote microglial activation." (PMID 37491366, 2023). "Core-binding factor is a large complex from Runx1-3 and core-binding factor B, which possesses important transcriptional regulatory properties, and Runx1 was induced after traumatic brain injury." (PMID 30559663, 2018).
Burkitt lymphoma (3 papers, 2014 to 2024). A rare form of malignant mature B-cell non-Hodgkin lymphoma. "Here we examined the requirement for basal Runx1 activity for tumor maintenance in the Eμ-Myc model of Burkitt's lymphoma." (PMID 27056890, 2016).
cardiac hypertrophy (3 papers, 2021 to 2025). "Our study first systematically evaluated the function and molecular mechanisms of Runx1 in cardiac hypertrophy, and we obtained some meaningful and innovative results." (PMID 34190420, 2021). "Findings from this study demonstrate Runx1 as a critical positive regulator of pathological cardiac hypertrophy." (PMID 34190420, 2021). "We used cardiac‐specific Runx1 knockdown (AAV9‐shRunx1) mice to characterize the role of Runx1 in TAC‐induced cardiac hypertrophy." (PMID 34190420, 2021). "In the present study, we investigated the role of Runx1 in experimentally pathological cardiac hypertrophy." (PMID 34190420, 2021). "Collectively, these data demonstrate that Runx1 contributes to the development of pathological cardiac hypertrophy in mice." (PMID 34190420, 2021). "Findings from our study demonstrate that expression of Runx1 was increased in pathological cardiac hypertrophy." (PMID 34190420, 2021). "In conclusion, we provide evidence that Runx1 expression increased in pathological cardiac hypertrophy." (PMID 34190420, 2021). "In summary, we conclude that Runx1 is a novel mediator and therapeutic target for pathological cardiac hypertrophy." (PMID 34190420, 2021). "We first explored Runx1 expression during cardiac hypertrophy in TAC‐induced cardiac hypertrophy mouse model." (PMID 34190420, 2021). "Remarkably, we demonstrated that Ro5‐3335 (a Runx1 inhibitor) acts as a potential therapeutic drug for treating pathological cardiac hypertrophy." (PMID 34190420, 2021). "Runx1 expression is increased in heart tissues from mice with pressure overload–induced cardiac hypertrophy and in neonatal rat cardiomyocytes in response to Ang II stimulation." (PMID 34190420, 2021). "First, we demonstrated Runx1 as a critical positive regulator of pathological cardiac hypertrophy for the first time." (PMID 34190420, 2021). "Some studies have shown that RUNX1 expression is increased in pathological cardiac hypertrophy." (PMID 37760803, 2023). "We therefore hypothesized that Runx1 might play a prominent role in progression of cardiac hypertrophy." (PMID 34190420, 2021). "Third, we first demonstrated that when use Ro5‐3335 (a Runx1 inhibitor), pathological cardiac hypertrophy could be alleviated." (PMID 34190420, 2021). "Moreover, in vivo studies confirmed that knockdown of Runx1 gene expression in cardiomyocytes alleviates pathological cardiac hypertrophy." (PMID 34190420, 2021). "Finally, targeting Runx1 is able to effectively inhibit progression of pathological cardiac hypertrophy." (PMID 34190420, 2021). "In addition, knockdown of RUNX1 expression alleviated pathological cardiac hypertrophy in vivo." (PMID 37760803, 2023). "The functional relevance of Runx1 expression in cardiac hypertrophy was unknown." (PMID 34190420, 2021).
cardiac hypertrophy (continued). "Moreover, knockdown of cardiac Runx1 alleviates the pressure overload–induced cardiac hypertrophy." (PMID 34190420, 2021). "Whether Runx1 participates in regulating pathological cardiac hypertrophy remains unclear." (PMID 34190420, 2021). "Since Runx1 has a crucial function in promoting cardiac hypertrophy, novel therapies targeting Runx1 may achieve an efficacious therapeutic response." (PMID 34190420, 2021).
diabetic nephropathy (3 papers, 2021 to 2026). "Transcription factors HIF1α, KLF4, KLF5, RUNX1, SP1, VDR and WT1 may be related to diabetic nephropathy." (PMID 34735495, 2021). "And transcription factors HIF1α, KLF4, KLF5, RUNX1, SP1, VDR, WT1 may be also related to diabetic nephropathy." (PMID 34735495, 2021).
diffuse large B-cell lymphoma (3 papers, 2011 to 2024). "MYCT1 binding to MAX probably suppressed RUNX1 transcription, leading to the inhibition of proliferation and cell cycle of the diffuse large B-cell lymphoma cells." (PMID 38172714, 2024). "MYCT1 may represses RUNX1 transcription by binding MAX in diffuse large B-cell lymphoma cells." (PMID 38172714, 2024).
dilated cardiomyopathy (3 papers, 2020 to 2025). Cardiomyopathy which is characterized by dilation and contractile dysfunction of the left and right ventricles. "In mice, Runx1 is induced in certain models of dilated cardiomyopathy and knockout of Runx1 in heart muscle improves recovery after heart injury." (PMID 39803985, 2025). "Interestingly, cardiac up-regulation of RUNX1 does not appear to be specific to ischaemic pathology as RUNX1 was also found to be increased experimentally in animal models of: (i) diabetic cardiomyopathy; (ii) pressure overload; and (iii) dilated cardiomyopathy." (PMID 32154891, 2020).
endometriosis (3 papers, 2021 to 2025). The growth of functional endometrial tissue in anatomic sites outside the uterine body. "Another study of the rat endometriosis model suggested that osteopontin, Lyn, Vav1, Runx1, and l-selectin play important roles in the pathogenesis of endometriosis based on gene expression profiling." (PMID 34220510, 2021).